RNASE1 (ribonuclease A family member 1, pancreatic)
Diseases named in the same sentence as RNASE1 in open-access papers (continued):
Sharing a sentence is not in itself a finding about the gene and the disease.
COVID-19 (4 papers, 2020 to 2023). A disease caused by infection with severe acute respiratory syndrome coronavirus 2. "In this study, we investigated a potential association between ribonuclease 1 and the outcome in COVID-19 patients and the impact of increased and decreased RNase 1 levels serum during the course of the disease." (PMID 37569802, 2023). "Interestingly, a significant difference in Horowitz score was observed at days 1 and 8, which may suggest that increasing RNase 1 levels over time in COVID-19 patients are associated with lung injury." (PMID 37569802, 2023). "Based on these results, there is now good evidence that increasing RNase 1 serum levels may play a role in renal dysfunction associated with COVID-19 and that increasing RNase 1 serum levels may be a potential biomarker to predict outcome in ICU patients with SARS-Cov-2 infection." (PMID 37569802, 2023). "We measured a significant correlation between the creatinine and RNase 1 serum levels in all patients on day two (p = 0.0007) and day four (p = 0.0004) after COVID-19 diagnosis." (PMID 37569802, 2023). "Next, we investigated the correlation between RNase 1 serum levels and 28-day mortality in COVID-19 patients." (PMID 37569802, 2023). "First, we wanted to analyze whether the RNase 1 serum levels increased or decreased in COVID-19 patients over two days or a week." (PMID 37569802, 2023). "Whether these critical situations can be counteracted in COVID-19 patients by intervention with RNase1 remains to be investigated." (PMID 33392206, 2020). "Taking these findings together, one can speculate that elimination of exRNA as an endogenous prothrombotic cofactor by RNase1 might help to reduce the adverse thrombotic complications in COVID-19 patients." (PMID 33392206, 2020). "Notably and in line with other works exploring COVID-19-induced transcriptome changes in a spatial context, we observed the downregulation of the RNase1 gene in SARS-CoV-2+ spots, potentially blocking the degradation of viral RNA in the environment of actively infected cells." (PMID 37858234, 2023). "In Cohort A, we measured a significant negative correlation between creatinine clearance and RNase 1 serum levels in all patients on day two (p = 0.0016) and day four (p = 0.0006) after COVID-19 diagnosis." (PMID 37569802, 2023).
prostate carcinoma (4 papers, 2017 to 2025). A carcinoma that arises from epithelial cells of the prostate gland. "In prostate cancer, the overexpression of RNASE1 is associated with poor survival." (PMID 36911389, 2023). "While in prostate cancer, overexpression of RNASE1 was associated with the poor survival." (PMID 34249481, 2021). "Indeed, certain glycoforms present in serum are derived from tumour cells, for example RNase 1 for pancreatic and PSA for prostate cancer, but in far lower amounts." (PMID 28657165, 2017).
Stroke (4 papers, 2012 to 2023). Sudden impairment of blood flow to a part of the brain due to occlusion or rupture of an artery to the brain. "Interestingly enough, administration of ribonuclease 1 (RNase 1) significantly reduced or prevented thrombus formation, stroke and development of edema in respective animal models." (PMID 23226277, 2012).
acute kidney injury (3 papers, 2020 to 2023). Sudden and sustained deterioration of the kidney function characterized by decreased glomerular filtration rate, increased serum creatinine or oliguria. "In previous studies, it was shown that serum RNase 1 serum levels are associated with the development of renal failure and positively correlated with serum creatinine in patients with leukemia." (PMID 37569802, 2023). "In addition, patients with higher serum RNase 1 levels were more likely to develop stage 3 acute kidney injury 48 h after surgery." (PMID 37569802, 2023).
colon cancer (3 papers, 2014 to 2023). "Notably, the effectiveness of EGFR-CD3 bsAb has been shown in preclinical studies, including those on glioblastoma, pancreatic, and colon cancers 74-77; for these tumor models, our findings suggest a synergistic antitumor effect when bsAb are combined with RNase1 treatment." (PMID 37416781, 2023).
leukemia (3 papers, 2019 to 2023). A malignant (clonal) hematologic disorder, involving hematopoietic stem cells and characterized by the presence of primitive or atypical myeloid or lymphoid cells in the bone marrow and the blood. "We used CRISPR–Cas9 mutagenesis to target the RNASE1 gene in the human leukemia cell line K562, which expresses RNASE1." (PMID 32609822, 2020).
myocardial infarction (3 papers, 2020 to 2023). Gross necrosis of the myocardium, as a result of interruption of the blood supply to the area, as in coronary thrombosis. "After myocardial infarction in mice systemic application of RNase1 reduced edema formation and infarct size and improved survival." (PMID 35388024, 2022). "In a mouse model of myocardial infarction, RNAse1 treatment reduced myocardial edema and infarct size." (PMID 35388024, 2022). "Thereby, RNase1 protects the endothelium from overwhelming inflammation by e.g., decreasing myocardial infarction size or thrombus formation, mainly via reduction of circulating eRNA levels, inflammatory cells and cytokines to recover physiological organ functions." (PMID 33178683, 2020).
renal dysfunction (3 papers, 2016 to 2023). "Consistent with this, our research group showed in a previous study that patients with renal dysfunction had significantly higher RNase 1 levels after TAAA repair than patients without renal dysfunction." (PMID 37569802, 2023). "In a previous study, we showed that patients with renal dysfunction had significantly higher RNase 1 levels after thoracoabdominal aortic aneurysm (TAAA) repair than patients without renal dysfunction." (PMID 37569802, 2023). "Patients with renal dysfunction revealed higher RNase 1 levels than without renal dysfunction (p = 0.03)." (PMID 26927088, 2016). "To investigate the role of RNase in SARS-CoV-2-induced renal dysfunction, we also investigated the correlation of RNase 1 levels with serum creatinine and creatinine clearance of patients with SARS-CoV-2 and the impact of increased and decreased RNase 1 levels during the course of the disease." (PMID 37569802, 2023).
breast tumor (2 papers, 2021 to 2023). "Collectively, these findings suggested that the RNase 1–EphA4 axis contributes to breast tumor progression and stemness by positively regulating tumor-initiating ability and enriching the CSC-like cell population." (PMID 33986289, 2021).
depression (2 papers, 2016 to 2025). "Among them, the expression levels of CIDEC, RNASE1, SLC36A1, and STYXL1 mRNA were significantly changed depending on the state of depression in the RT-qPCR analysis, which was consistent with the results of the microarray analysis." (PMID 26926397, 2016).
heart failure (2 papers, 2015 to 2016). Inability of the heart to pump blood at an adequate rate to meet tissue metabolic requirements. "Furthermore, the RNASE1 mRNA level in peripheral mononuclear cells is 5-fold higher in patients with heart failure than in controls." (PMID 26926397, 2016).
lung carcinoma (2 papers, 2014 to 2025). "This was further supported by the evidence that RNase1/ALK co-expression is significantly correlated with worse survival in patients with lung cancer from the TCGA database." (PMID 40246819, 2025). "Together, these results suggested that the RNase1-driven-ALK-activation (RDAA) in lung cancer cells enhances cell proliferation, mobility and cellular transformation in vitro." (PMID 40246819, 2025). "Among those, only four lung cancer cell lines exhibited RNase1 and ALK co-expression with ALK phosphorylation, suggesting that RNase1 is required for ALK activation in lung cancer cells." (PMID 40246819, 2025). "Clinical data analysis further revealed that co-expression of RNase1 and ALK strongly correlated with poorer survival outcomes in lung cancer patients." (PMID 40246819, 2025). "In both EPHA4 wild-type or EPHA4 knockout lung cancer cells, RNase1 could bind to ALK and ALK did not bind to EPHA4, which suggested that the RNase1-ALK interaction was independent of EPHA4 in lung cancer cells." (PMID 40246819, 2025). "In this study, we report a non-canonical role of human secretory ribonuclease 1 (RNase1), which binds to and activates wild-type ALK in lung cancer cells, thereby triggering its downstream signaling pathway." (PMID 40246819, 2025). "Next, mice subcutaneously injected with H1299 control (without RNase1 expression), RDAA (ALK and RNase1 co-expression), or ALK mut lung cancer cells (EML4-ALK expression) were treated with ceritinib for two weeks (25 mg/kg/day)." (PMID 40246819, 2025). "Interestingly, among the 13 ribonucleases, only RNase1 (R1), but not the others, bound to endogenous ALK in H1299 human lung cancer cells expressing WT ALK." (PMID 40246819, 2025).
Obesity (2 papers, 2025). Accumulation of substantial excess body fat. "Notably, in men with obesity and DM2, the genes up-regulated due to bright light include fibroblast growth factor 1 (FGF1), vasorin (VASN), ribonuclease A family member 1 (RNASE1), pappalysin 1 (PAPPA), Interleukin 7 (IL7), and fatty acid binding protein 3 (FABP3)." (PMID 40981208, 2025).
asthma (1 paper, 2023). "In contrast, allograft rejection, asthma, graft versus host disease, primary immunodeficiency, and type I diabetes mellitus significantly enriched the low RNASE1 subgroup." (PMID 38013304, 2023).
autism (1 paper, 2024). Persistent deficits in social interaction and communication and interaction as well as a markedly restricted repertoire of activity and interest as well as repetitive patterns of behavior. "Among the autism risk genes, those involved in transcriptional regulation, such as RNASE1 and TCF7L2, are predominantly expressed in the early stages of this lineage." (PMID 39363111, 2024).
brain edema (1 paper, 2022). Increased intracellular or extracellular fluid in brain tissue. "First, the influence of LD RNase1 on post-CCI brain edema was examined by measuring the brain water content by vacuum drying." (PMID 35388024, 2022).
cerebral infarction (1 paper, 2020). An ischemic condition of the brain, producing a persistent focal neurological deficit in the area of distribution of the cerebral arteries. "Remarkably, RNase1 administration reduces myocardial as well as cerebral infarction size and preserves cellular function in the same pathological context." (PMID 33178683, 2020).
diabetes mellitus (1 paper, 2023). A metabolic disorder characterized by abnormally high blood sugar levels due to diminished production of insulin or insulin resistance/desensitization. "Only eight patients were diagnosed with diabetes mellitus, and all eight patients belonged to the increasing RNase 1 group (p = 0.0124)." (PMID 37569802, 2023).
Disseminated intravascular coagulation (1 paper, 2023). Disseminated intravascular coagulation is characterized by the widespread activation of coagulation, which results in the intravascular formation of fibrin and ultimately thrombotic occlusion of small and midsize vessels. "Future studies will tell whether RNase1-based therapies may allow to tackle other cases of chronic neuroinflammation, disseminated intravascular coagulation, or even long-Covid syndrome as a scenario of “runaway inflammation”." (PMID 37550658, 2023).
head and neck cancer (1 paper, 2025). A primary or metastatic malignant neoplasm affecting the head and neck. "Moreover, an analysis of the GENT2 database revealed that RNase1 expression is not only elevated in head and neck cancer and oral cancer but also in cancer cell lines across various types compared with that in normal tissues and cell lines." (PMID 39932384, 2025).
Hepatic steatosis (1 paper, 2023). Steatosis is a term used to denote lipid accumulation within hepatocytes. "Histological evaluation of the livers of the mice fed with the NC, HFMCD diet, and HFMCD diet with RNase 1 intervention showed a marked increase in hepatic steatosis in the HFMCD diet-fed group, and its reduction upon RNase 1 co-administration." (PMID 37484201, 2023). "Similarly, RNase 1 administration significantly improves hepatic steatosis, inflammatory and injury markers in a murine NASH model." (PMID 37484201, 2023). "Additionally, PA-induced hepatic steatosis was also reduced by RNase 1 administration." (PMID 37484201, 2023).
Hypertension (1 paper, 2023). The presence of chronic increased pressure in the systemic arterial system. "Still, an increased expression of SVEP1, NRP1, RNASE1, QSOX1, and GKN1, along with decreased expression of XYLT2, CFH, LEP, and CETP serum levels were found in patients with hypertension." (PMID 37792298, 2023).
keloid (1 paper, 2022). An irregularly shaped, elevated mark on the skin caused by deposits of excessive amounts of collagen during wound healing. "Furthermore, two modules of macrophages (Module2: highly expresses RNASE1, C1QA, CD163, CD14, C1QC, FCGRT, and MS4A7; Module10: highly expresses APOC1, CTSB, CTSL, and TYROBP), which exhibited the characteristics of TAMs, increased significantly in keloid." (PMID 35990663, 2022).
non-small cell lung carcinoma (1 paper, 2025). A group of at least three distinct histological types of lung cancer, including non-small cell squamous cell carcinoma, adenocarcinoma, and large cell carcinoma. "In current study, we focus on the oncogenic mechanism in non-small cell lung cancer patients without typical gene mutations or rearrangements/fusion and report a non-canonical role of RNase1, a human ribonuclease superfamily protein, as a ligand of wild-type ALK." (PMID 40246819, 2025).
pneumococcal infection (1 paper, 2016). Infections with bacteria of the species streptococcus pneumoniae. "However, further studies utilizing murine model of pneumococcal infection are needed to validate whether the administration of RNase1 may prevent the development of S. pneumoniae-driven infection diseases." (PMID 27892961, 2016).
Primary immunodeficiency (1 paper, 2023). "Primary immunodeficiency was enriched in subgroups with low expression of CYSTM1 and low expression of RNASE1." (PMID 38013304, 2023).
respiratory failure (1 paper, 2016). The significant impairment of gas exchange within the lungs resulting in hypoxia, hypercarbia, or both, to the extent that organ tissue perfusion is severely compromised. "RNase 1 and 3 were higher in respiratory failure than without respiratory failure (p < 0.0001 and p = 0.02, respectively)." (PMID 26927088, 2016).
rheumatoid arthritis (1 paper, 2024). A chronic, systemic autoimmune disorder characterized by inflammation in the synovial membranes and articular surfaces. "The expression of RNase1 was also observed to increase in the synovium of rheumatoid arthritis." (PMID 39205658, 2024).
Sjögren's syndrome (1 paper, 2023). "Here, recent developments of an IgG1-Fc-fusion protein with RNase1, designated RSLV-132, proved its availability in phase-II studies of inflammatory diseases such as Sjögren's syndrome." (PMID 37550658, 2023).
steatosis (1 paper, 2023). Increased lipid within the cytoplasm of cells. "The outcomes regarding steatosis, inflammation, and hepatic ballooning were assessed histologically using the NAFLD activity score, which significantly decreased upon RNase 1 treatment." (PMID 37484201, 2023).
subarachnoid hemorrhage (1 paper, 2024). A serious neurological disorder characterized by intracranial hemorrhage into the subarachnoid space. "In addition, the intravenous application of RNase A (the bovine equivalent to human RNase 1) was reported to alleviate subarachnoid hemorrhage through the abrogation of NET burden in the brain parenchyma." (PMID 38188146, 2024).
T-cell leukemia (1 paper, 2021). A malignant disease of the T-lymphocytes in the bone marrow, thymus, and/or blood. "The amino acid substitutions in RNase 1 diminish its affinity for RI by 106-fold and confer high toxicity for T-cell leukemia cells." (PMID 34702287, 2021).
cancer (63 papers, 2010 to 2025). A tumor composed of atypical neoplastic, often pleomorphic cells that invade other tissues. "RNase1 expression is positively associated with exhausted T‐cell gene signatures and immune checkpoint proteins across several cancer types." (PMID 39932384, 2025). "Here, ribonuclease 1 (RNase1) causes T‐cell dysfunction and promotes exhausted T‐cell signatures in cancers." (PMID 39932384, 2025). "RNASE1, a member of the ribonuclease A superfamily, exhibits bidirectional regulatory properties in the tumor microenvironments of various cancer types, which may be associated with its RNA degradation activity and the heterogeneity of the tumor microenvironment." (PMID 41252877, 2025). "It is possible that endogenous RIs are sufficient to inhibit the enzymatic activity of RNase1 under both physiological and pathological conditions, or that cancer cells increase RI expression to repress intracellular RNA digestion by RNase1." (PMID 39932384, 2025). "To determinate the role of T cell subsets in T‐cell cytotoxicity repressed by RNase1, we first tested which T cell subsets were responsible for the primary T‐cell cytotoxicity against cancer cells." (PMID 39932384, 2025). "Overall, the study supports the immunosuppressive role of RNase1 in cancer of negatively regulating STAT1 to impair CD8+ T‐cell cytotoxicity." (PMID 39932384, 2025). "For instances, ribonuclease 1 (RNase1), RNase4, RNase5, and RNase7 have been reported to function as ligands for cell membrane receptors, promoting cancer malignancy independently of their ribonucleolytic activity." (PMID 39932384, 2025). "Compared to control cells, mouse RNase1 expression in E0771‐OVA cells led to a dramatically increased cancer growth." (PMID 39932384, 2025). "Here, tumor volume and weight can be diminished by RNase1 treatment in a human subcutaneous xenograft cancer model." (PMID 33015070, 2020). "By means of site-directed mutagenesis D’Alessio and colleagues developed artificial dimers of RNase A and RNase 1 that showed cytotoxicity towards cancer cells." (PMID 31572192, 2019). "Recent focus has shifted to the protective role of RNase 1 in mitigating inflammation at sites of tissue damage, vascular disease, or cancer by degrading eRNA." (PMID 30463297, 2018). "In subcutaneous xenograft models of human cancer, RNase1 strongly counteracted the tumorigenic activities of eRNA25." (PMID 27892961, 2016). "In contrast, the present study is the first to identify a cancer marker that distinguishes patients with PaCa by detecting altered levels of N-glycosylation of a specific amino acid residue, Asn88, in RNase1." (PMID 25336120, 2014). "Cancer cells expressing RNase1 are resistant to CD8+ T‐cell‐mediated killing." (PMID 39932384, 2025). "Subsequent analysis of mouse cancer tissues through flow cytometry revealed that RNase1 knockdown in 4T1 cells increased the proportion of CD8+ T cells expressing effector cytokines, including granzyme B (GB) and IFN‐γ, and reduced expression of ICs such as Pd‐1 and Tim‐3 on CD8+ T cells in the TME." (PMID 39932384, 2025). "Therefore, we further assessed the inhibition of T‐cell cytotoxicity by RNase1 in CD8+ T cells using a time‐course measurement of T cell‐mediated cancer cell killing effect." (PMID 39932384, 2025). "To verify whether RNase1‐induced T‐cell dysfunction possesses clinical implications and potential applications, we analyzed cancer patient tissues from the online databases." (PMID 39932384, 2025). "RNase1 enables cancer cells to prevent CD8+ T‐cell attacks through signal transducer and activator of transcription 1 (STAT1) inactivation, causing T‐cell dysfunction and underscoring RNase1's immunosuppressive role." (PMID 39932384, 2025). "Targeting the RNase1‐STAT1 interaction could prevent CD8+ T‐cell dysfunction in RNase1‐highly expressing cancer patients." (PMID 39932384, 2025).